GLO1 (glyoxalase I)
Diseases named in the same sentence as GLO1 in open-access papers (continued):
Sharing a sentence is not in itself a finding about the gene and the disease.
type 2 diabetes (14 papers, 2018 to 2025). "It is notable that although we have identified that there is an association with a type 2 diabetes‐associated variant (rs2490026‐C) and a GLO1 eQTL, it is possible this eQTL affects GLP1R given that the same variant was associated with multiple genes." (PMID 39838854, 2025). "Edwin’s team found that GLO1 expression in the skeletal muscle of type 2 diabetic patients is regulated by NAMPT/SIRT, and supplementation with NR prevented the reduction of GLO1 expression and activity." (PMID 40775221, 2025). "Exosomes derived from adipose-derived stem cells overexpressing GLO-1 protected the endothelial cells and promoted the angiogenesis in type 2 diabetic mice with limb ischemia, which will be a promising clinical treatment in diabetic lower limb ischemia." (PMID 34266474, 2021). "Metformin, an oral glucose-lowering agent for type 2 diabetes, increases GLO1 activity and was shown to lower circulating MG levels in patients with type 2 diabetes." (PMID 33143048, 2020). "This study purpose was to assess the vitamin D supplementation effectiveness on GLO1 and RAGE genes expression and also on AGES and TNF-α serum level in type 2 diabetic patients." (PMID 31673295, 2019). "By contrast, GLO1 activity was increased in red blood cells of streptozotocin-induced diabetic C57BL/6 mice, compared to non-diabetic controls and GLO1 activity was increased in the red blood cells of patients with type 1 diabetes and type 2 diabetes, compared to healthy control subjects." (PMID 33143048, 2020).
hepatocellular carcinoma (13 papers, 2016 to 2025). A malignant tumor that arises from hepatocytes. "Having established a relationship between a high fat diet and decreased expression of GLO1 in the murine model, we explored the potential underlying regulatory mechanism in liver cells in vitro using the hepatoma cell line HepG2." (PMID 29456458, 2018). "Currently, high GLO1 expression has been confirmed in various malignant tumors, including gastric cancer, pancreatic cancer, endometrial cancer, hepatocellular carcinoma, and prostate cancer, and is closely associated with tumor invasion, metastasis, and chemotherapy resistance." (PMID 40352588, 2025). "A similar role of Glo1 has also been validated in hepatocellular carcinoma and downregulation of Glo1 enhanced tumor growth." (PMID 35898868, 2022). "Zender and collaborators identified and validated GLO1 as a tumor suppressor gene in hepatocellular carcinoma and knockdown of GLO1 using short hairpin RNAs (shRNAs) increased tumor growth in vivo." (PMID 30674353, 2019). "In human hepatoma HepG2 cells and BJ fibroblasts the incubation with SR led to a significant increase of Glo1 activity and to a related dose-dependent increase in Glo1 mRNA levels." (PMID 30445774, 2018). "Also, FAs treatment of hepatoma cells (HepG2), which led to lipids accumulation in the cells, downregulated Glo1 and elevated MGO levels." (PMID 40141037, 2025). "Similarly, GLO1 inhibitors have been shown to limit tumor progression and increase the sensitivity of conventional anticancer therapeutic agents in colorectal cancer, melanoma, hepatocellular carcinoma, and gastric cancer." (PMID 40352588, 2025). "Hence, decrease of Glo-1 activity and hepatic dicarbonyl stress in NAFLD with progression to NASH may also increase risk of hepatocellular carcinoma." (PMID 27338619, 2016). "Moreover, in a mouse model of hepatocellular carcinoma, Glo-1 was a tumour suppressor protein." (PMID 27338619, 2016). "Glo1 inducer activity of tRES+HESP was then validated in human endothelial cells and fibroblasts in primary culture and the HepG2 hepatoma, hepatocyte-like cell line." (PMID 40867852, 2025). "Pharmacological modulation of Glo-1 as well as silencing of RAGE have shown promise in preclinical models of CCl4-induced liver fibrosis and hepatocellular carcinoma, respectively." (PMID 38187538, 2023). "Decreased levels of Glo-1 and increased intracellular dicarbonyl stress occurs in liver fibrosis, cirrhosis, non-alcoholic steatohepatitis (NASH) and hepatocellular carcinoma." (PMID 38187538, 2023). "The aim of this study was to explore, for the first time, health-beneficial gene expression other than Glo1 induced by tRES+HESP in human endothelial cells and fibroblasts in primary culture and HepG2 hepatoma cell line and activity of cis-resveratrol (cRES) as a Glo1 inducer." (PMID 40867852, 2025).
melanoma (13 papers, 2014 to 2025). A malignant, usually aggressive tumor composed of atypical, neoplastic melanocytes. "It was recently revealed that CRISPR/Cas 9-based GLO1 deletion from human A375 malignant melanoma cells changes redox homeostasis, which is associated with acceleration of carcinogenesis." (PMID 37238995, 2023). "CHG is a potent inhibitor of Glo1, and its rapid release in melanoma tissue inhibits Glo1, causing an increase in intracellular MGO levels, resulting in tumor growth inhibition." (PMID 33396745, 2020). "Recently, we have reported the overexpression of glyoxalase 1 (encoded by GLO1), a glutathione-dependent enzyme involved in detoxification of the reactive glycolytic byproduct methylglyoxal, in human malignant melanoma cell culture models and clinical samples." (PMID 32466621, 2020). "Recently, we have reported the overexpression of glyoxalase 1 (encoded by GLO1), a glutathione-dependent enzyme involved in the detoxification of the reactive glycolytic byproduct methylglyoxal, in human malignant melanoma cell culture models and clinical samples." (PMID 32466621, 2020). "In addition, it has been very recently observed that the expression of PD-L1 is attenuated in Glo1-knockout malignant melanoma cells, thus suggesting a potential causative role of Glo1 in controlling PD-L1 expression in this neoplasia, and possibly also in mPCa." (PMID 34199263, 2021). "Our previous studies have demonstrated the upregulation of GLO-1 expression in human malignant melanoma tissue." (PMID 40727469, 2025). "Studies employing cell culture models, patient samples, and tissue microarray analysis have previously shown that GLO-1 is overexpressed during melanoma progression." (PMID 40727469, 2025). "In a separate study employing CRISPR/Cas 9-mediated deletion of GLO-1 in both in vivo and in vitro models, we established a novel function for GLO-1 in promoting melanoma cell invasiveness and metastasis." (PMID 40727469, 2025). "GLO1 has recently been shown to be overexpressed in human malignant melanoma cells and patient tumours, supporting its new function as a molecular regulator of invasion and metastasis in melanoma." (PMID 37238995, 2023). "As Glo1 is highly expressed in both melanoma and non-melanoma skin cancer, we proposed that Glo1 is a novel target in skin cancer and more extensive studies are necessary in future animal and clinical studies for future drug development against skin cancer." (PMID 33396745, 2020). "Using KO (KO_B40 and KO_C2) versus rescue clones (B40_R and C2_R)], it was then observed that an impaired transwell migration potential (characteristic of A375 malignant melanoma cells with GLO1 deletion) can be fully restored by CMV-driven GLO1 re-expression." (PMID 32466621, 2020). "His team showed that Glo1 inhibition increased MGO-induced cytotoxicity in human melanoma cells and observed heat shock protein 27 as the target protein of post-translation by MGO in metastatic melanoma cells." (PMID 33396745, 2020). "Here, we report the identification of GLO1 as a novel molecular determinant of invasion and metastasis in experimental human malignant melanoma observable in vitro and in vivo." (PMID 32466621, 2020). "Next, a SCID mouse metastasis model of human melanoma was employed assessing GLO1-modulation of lung tumorigenesis after tail vein injection of melanoma cells." (PMID 32466621, 2020). "Downregulation of Glo1 by miR-137 inhibits melanoma cell proliferation, whereas re-expression of Glo1 reduces the inhibitory effect of miR-127 on melanoma cell proliferation, suggesting that Glo1 expression is essential for melanoma proliferation." (PMID 33396745, 2020). "Taken together, these prototype data provide evidence in support of a novel function of GLO1 in melanoma cell invasiveness and metastasis, and ongoing investigations explore the function and therapeutic potential of GLO1 as a novel melanoma target." (PMID 32466621, 2020).
melanoma (continued). "After demonstrating EMT impairment as a function of genetic GLO1 deletion, further genetic evidence in support of a critical role of GLO1 in melanoma invasion and metastasis was generated." (PMID 32466621, 2020). "Recently, we have published our observation that GLO1 is overexpressed in human malignant melanoma, detectable in cell culture models and patient samples." (PMID 32466621, 2020). "Here, using genetic target modulation, we report the identification of GLO1 as a novel molecular determinant of invasion and metastasis in malignant melanoma." (PMID 32466621, 2020). "GLO1 re-expression was confirmed in transfectants by RT-qPCR analysis of GLO1 mRNA levels and detection of specific enzymatic activity, performed in A375 melanoma cell lines (WT, B40, C2, B40R, C2R)." (PMID 32466621, 2020). "Using genetic target modulation, we report the identification of GLO1 as a novel molecular determinant of invasion and metastasis in malignant melanoma." (PMID 32466621, 2020). "Here, using genetic target modulation, we have identified GLO1 as a novel molecular determinant of invasion and metastasis in malignant melanoma." (PMID 32466621, 2020). "First, A375 human malignant melanoma cells with GLO1 deletion (A375-GLO1_KO) were engineered using CRISPR/Cas9, and genetic rescue clones were generated by stable transfection of KO clones employing a CMV-driven GLO1 construct (A375-GLO1_R)." (PMID 32466621, 2020). "The change in GLO1 mRNA expression has been previously reported in several human cancers including cancer breast, cancer colon and in malignant melanoma." (PMID 29321821, 2017). "It has been shown that Glo-1 expression and activity is increased in many human cancer types such as colon, prostate, melanoma, lung, and breast and that Glo-1 overexpression is correlated with cancer progression and drug resistance." (PMID 24978626, 2014). "Furthermore, CRISPR/Cas9-based GLO-1 deletion and rescue experiments have uncovered a novel function for GLO-1 as a molecular regulator of invasion and metastasis in melanoma." (PMID 40727469, 2025). "Additionally, we explored the potential of GLO-1 expression to predict response to PD1 immunotherapy, finding significant associations in melanoma, glioblastoma, kidney cancer, and bladder cancer." (PMID 40727469, 2025). "In order to resolve these relevant questions, we are currently pursuing an experimental approach involving CRISPR/Cas9-based genetic target elimination that we have implemented successfully to explore the role of GLO1 in cancer cell lines including A375 malignancies melanoma and DU-145 PCa cells." (PMID 34298821, 2021). "Taken together, these genetic rescue data provide strong experimental evidence supporting a novel role of GLO1 expression as a critical molecular determinant of EMT-like characteristics in A375 malignant melanoma cells, observable at both the gene expression and phenotypic levels." (PMID 32466621, 2020). "Following our earlier research on GLO1 overexpression observable during melanoma patient progression, we have now employed CRISPR/Cas 9-based GLO1 deletion and rescue expression, allowing stringent genetic target modulation as examined in A375 human malignant melanoma cells." (PMID 32466621, 2020). "Likewise, an impaired potential for invasion, as assessed by Matrigel transwell assays (characteristic of A375 malignant melanoma cells with GLO1 deletion), was fully reversed by CMV-driven GLO1 re-expression." (PMID 32466621, 2020). "Taken together, these data provide strong genetic evidence in support of a novel function of GLO1 in melanoma cell invasiveness and metastasis, and our ongoing investigations explore the function and therapeutic potential of GLO1 as a novel molecular target in melanoma metastasis." (PMID 32466621, 2020).
melanoma (continued). "However, more detailed follow up studies will have to examine the role of GLO1 deletion in a genetically diverse set of representative human melanoma cell lines to further substantiate our prototype data." (PMID 32466621, 2020). "EMT is now an established molecular pathway involved in melanoma progression, recognized also as an important therapeutic target, and our array analysis identified a number of EMT-regulatory genes responsive to GLO1 status implicated mechanistically in metastatic melanoma." (PMID 32466621, 2020). "As expected, it was observed that genomic depletion of GLO1 expression sensitizes A375_GLO1_KO melanoma cells to methylglyoxal (500 μm; 24 h) cytotoxicity, as assessed by flow cytometric viability analysis of annexinV-PI stained cells (center panels and bottom bar graph)." (PMID 32466621, 2020). "If pharmacological target modulation phenocopies the changes caused by CRISPR/Cas9-based genetic target modulation, drug-like GLO1 inhibitors might emerge as a novel class of molecular therapeutics for the suppression of invasion and metastasis in malignant melanoma patients." (PMID 32466621, 2020). "Taken together, these data demonstrate that CRISPR/Cas 9-mediated deletion of GLO1 does not impact proliferative capacity while causing significant sensitization to methylglyoxal-, chemotherapy-, and starvation-induced cytotoxic stress in A375 malignant melanoma cells." (PMID 32466621, 2020). "Providing further evidence in support of GLO1 expression as a mechanistic determinant of melanoma cell invasiveness, differential expression of MMP9 as a function of GLO1 status was substantiated by enzymatic activity and ELISA analysis." (PMID 32466621, 2020). "A375 melanoma tumour development and metastasis can be dysregulated in opposite ways as a result of GLO1 deletion, as was shown by the observation of an enhanced growth rate of GLO1 KO tumours in a SCID mouse melanoma xenograft model, together with TXNIP overexpression and metabolic reprogramming." (PMID 37238995, 2023). "Among the Glo1 inhibitors, intravenous administration of glycyl, the glutamyl diethyl ether form of S-(N-p-chlorophenyl-N-hydroxycarbamoyl) glutathione (CHG), inhibits melanoma tumor growth." (PMID 33396745, 2020). "Mir-137 can inhibit the migration and invasion of melanoma cells 45–47 by targeting various mRNAs such as PIK3R3, TBX3, c-Met, YB1, EZH2, and MITF, and inhibit the proliferation and promote the apoptosis of melanoma cells by competitive binding to genes such as SLC1A5, GLO1, CDK6, etc.." (PMID 33194692, 2020). "In addition to melanoma, non-melanoma SCC and BCC also showed overexpression of Glo1, which makes Glo1 a potential target in skin malignancies." (PMID 33396745, 2020). "Glo1 is also overexpressed in both melanoma and non-melanoma cells." (PMID 33396745, 2020). "Moreover, the study found that GLO1 KO condition reduced PDL1 expression, both at the mRNA and protein levels (GLO1 WT versus GLO1 KO [B40 and C2]), a noteworthy finding given the significance of PD-L1 as a key target for clinically relevant melanoma immunotherapeutic intervention." (PMID 37238995, 2023).
atherosclerosis (12 papers, 2014 to 2025). A disease characterized by the build-up of fatty material and calcium deposition in the arterial wall resulting in partial or complete occlusion of the arterial lumen. "Metformin treatment in patients with T2DM and atherosclerosis, besides its hypoglycemic effect, is associated with increased Glo1 activity." (PMID 38067472, 2023). "Even less is known about the role of Glo1 in metabolism, particularly in hyperlipidaemia being one of the main risk factors for atherosclerosis." (PMID 26788517, 2016). "We have tested if GLO1 overexpression can protect against accelerated atherosclerosis in STZ‐treated apolipoprotein E‐deficient (Apoe−/−) mice and if GLO1 knockdown can promote atherogenesis in nondiabetic Apoe−/− mice." (PMID 24920125, 2014). "Future studies that focus on the long-term effects in atherosclerosis susceptible models with significant genetic or environmental challenges could yield more power in elucidating the potential causal role of Glo1 in atherosclerosis." (PMID 39896461, 2025). "In addition, chemical inhibition of Glo1 has been shown to induce atherosclerosis in ApoE deficient mice." (PMID 26788517, 2016). "Largely in line with our atherosclerosis experiment, this study only found a modest reduction in dicarbonyl stress in the hearts of the Glo1-overexpressing mice." (PMID 40722867, 2025). "GLO1 is the main opponent of the degradation of the reactive metabolite methylglyoxal, and plays an important role in the progression of atherosclerosis and plaque rupture." (PMID 34680994, 2021). "Future studies using Glo1 knockout mice with a complete reduction of the Glo1 activity will be needed in order to finally work out the role of Glo1 in atherosclerosis and metabolism." (PMID 26788517, 2016). "In order to study the role of Glo1 in the progress of atherosclerosis, double transgenic Glo1KD × ApoE−/− mice were created." (PMID 26788517, 2016). "However, the transcriptomic profiling of aorta provided supportive links between Glo1 and atherosclerosis." (PMID 39896461, 2025). "In line, the elevated Glo-1 expression induced by RAGE deficiency as observed in the current study did not impact atherosclerosis." (PMID 30323247, 2018). "In this study, Glo1 was further investigated in an in vivo model of Glo1 knockdown (Glo1KD) mice, to determine its distinct role in metabolism under different mouse diets and progression of atherosclerosis." (PMID 26788517, 2016). "It will be interesting to see whether this enzyme or other mechanisms can overcome effects of reduced Glo1 activity in the context of atherosclerosis." (PMID 26788517, 2016). "However, the function of Glo1 in macrovascular disease, particularly atherosclerosis, still remains uncertain." (PMID 26788517, 2016). "Our inability to demonstrate atheroprotection with GLO1 overexpression or increased atherosclerosis in Glo1KD mice may, in part, reflect that, in Apoe−/− mice, cholesterol is primarily associated with remnant particles and not with LDL as is the case in humans." (PMID 24920125, 2014). "With respect to atherosclerosis, the knockdown of Glo1 did not enhance the formation of atherosclerotic plaques in the aortic arch analyzed via en face preparations." (PMID 26788517, 2016). "In contrast, the Glo1 knockdown in double transgenic mice did not have any impact on atherosclerosis of the upper aorta." (PMID 26788517, 2016). "Although the GLO1 transgene did not protect Apoe−/− mice from accelerated atherosclerosis after STZ treatment, it appeared to reduce MG‐H1 immunoreactivity in aortic extracts from diabetic animals." (PMID 24920125, 2014). "Glo1 levels were about 50% lower in cardiac tissues from HIV+ with HF as compared to HIV- with no HF and 35 ± 5.1% lower than HIV- group with atherosclerosis and HF." (PMID 34970611, 2021).